CDK4 (cyclin dependent kinase 4)
Diseases named in the same sentence as CDK4 in open-access papers (continued):
Sharing a sentence is not in itself a finding about the gene and the disease.
cancer (continued). "Although various methods have been tried to overcome therapeutic resistance in the different types of cancer, only two agents, mTOR inhibitor and CDK4/6 inhibitor, are currently available in the management of endocrine resistance, and there are still unmet therapeutic needs to improve outcomes." (PMID 34407787, 2021). "Thus, we tested the effect of CDK4/6/HSP90 dual targeting on HIF1α expression in various cancer cell lines." (PMID 34686682, 2021). "We analyzed the prognostic relevance of CDK2, CDK4, and CDK6 genetic alterations and found that CDK4 and CDK6 alterations are associated with low overall survival, disease-free survival, and progression-free survival of cancer cohorts (p < 0.05)." (PMID 33668805, 2021). "We propose that a CDK2/4/6 triple-inhibitor may offer some advantages over CDK4/6 dual-inhibitor in providing broader patient selection, higher efficacy, and broader types of cancers for treatment." (PMID 33579185, 2021). "Clinical CDK4/6 inhibitors are used and tested to treat a variety of cancer types." (PMID 34099663, 2021). "Dysregulation of CDKs, such as CDK1, CDK2, CDK3, CDK4 and CDK6, is a well-known hallmark of cancer." (PMID 34778245, 2021). "CDK4/6i could be administered before/alongside S-phase or mitotic-targeting compounds; in other cancers (including ovarian and bladder), this form of administration can lead to protection from the cytostatic or cytotoxic effects of CDK4/6i." (PMID 34828525, 2021). "Cancer cells resistant to CDK4/6 inhibitor also are resistant to KDM6B inhibition." (PMID 34893606, 2021). "Numerous cancers have been found to be particularly sensitive to CDK4/6 inhibition." (PMID 33805800, 2021). "Overexpression of CDK4 could induce uncontrolled cell growth and eventually lead to tumorigenesis; moreover, amplification of the CDK4 gene, have been found in various cancers." (PMID 33995474, 2021). "CDK4/6i has remarkable clinical utility in the treatment of cancer." (PMID 34459131, 2021). "For these patients, as well as those who had progression after treatment with CDK4/6 inhibitors, chemotherapies should be considered at an early treatment phase to eliminate the highly malignant tumors, and then followed by maintenance therapy that is less toxic." (PMID 34503209, 2021). "Due to the important roles of CDK2 in HCC, a CDK2/4/6 triple inhibitor may have additional advantages and broader anti-cancer activities than CDK4/6 dual inhibitors for the treatment of human HCC and other cancers." (PMID 33579185, 2021). "That is, cancer cells exiting mitosis with low levels of CDK2 (quiescent cells) would strictly depend upon CDK4/6 function to re-enter the cell cycle, whereas cells exiting mitosis with high levels of CDK2 (proliferating cells) would bypass the requirement for CDK4/6 activity." (PMID 33239679, 2021). "Search strategy: Eligible articles were identified by a search of existing literature for the period 2005/01/01–2021/01/01; The algorithm consisted of a predefined combination of the following keywords “breast”, “cancer”, “aromatase inhibitors”, “CDK4/6”, “phase III”." (PMID 33530456, 2021). "Abemaciclib, a CDK4/6 inhibitor, induces senescence in cancer cells." (PMID 34761877, 2021). "In order to explore the molecular mechanism via which CDC37L1 inhibited GC cell proliferation and migration, we detected the expression of several cancer signaling pathway factors, such as CDK4, CDK6, Cyclin D1, FAK, PI3K-P110 and mTOR through western blot assays." (PMID 33976724, 2021). "CDK4/6 inhibitors inhibit the proliferation of cancer cells by suppressing retinoblastoma (RB) phosphorylation and maintaining the repressive effect of RB on the E2F family, thereby reducing the transcription of pro-proliferative proteins and inhibiting cell cycle progression." (PMID 34026622, 2021).
cancer (continued). "Moreover, RABL6A is a potent oncoprotein that controls many druggable cancer targets besides CDK4/6 and MEK, including Myc, PP2A-Akt-mTOR, and receptor tyrosine kinase pathways like VEGFR and EGFR." (PMID 33456709, 2021). "In light of the extensive number of cellular systems in which cellular senescence has been studied, therapies that induce senescence as part of their anti-cancer effects, such as cyclin-dependent kinase 4 and 6 (CDK4/6) inhibitors, will be used to illustrate key concepts and functional connections." (PMID 34360912, 2021). "Moreover, a CDK4/6-RB integrated signature, identified from a recent pan-cancer molecular analysis, was also found to be overrepresented in fusion-induced MEC." (PMID 33830080, 2021). "Furthermore, alterations in the associated genes (CDK-1, CDK-4, CCNE1, CDKN2A, RBI, NCAPG, AURKA, and CCND2) were determined in five CRC studies (CRC, TCGA, Firehose, CRC, TCGA, Nature, CRC, Pan-Cancer, MSKCC and CPTAC-2)." (PMID 33732631, 2021). "However, expressions of CDK2 and that of CDK4 correlated with CAF infiltrations in cohorts of 14 cancer types." (PMID 33668805, 2021). "The major mechanism of action of CDK4/6i is to block the cell cycle at the G1 to the S transition phase, which could prevent the proliferation of cancer cells." (PMID 34459131, 2021). "Overall, the authors showed that, by regulating the SASP following CDK4/6 inhibition, the stemness of the cancer cells could be repressed via the IL‐6‐STAT3 axis." (PMID 34137158, 2021). "New research has also shown that TRAF1 affects the cell cycle in cancer in a CDK4‐dependent manner." (PMID 33452764, 2021). "Interestingly, fatty acid oxidation has also been shown to play a role in CDK4 regulated metabolic reprogramming in other cancers." (PMID 33572972, 2021). "RB1 mutation could be acquired, albeit at a lower rate (~5%), after exposure to CDK4/6i in the clinical setting, establishing a feedback loop by which cancer cells evade cell cycle checkpoint inhibition." (PMID 34508104, 2021). "We found that aminoquinol could effectively reduce the viability of the Rb negative Hep3B cells (IC50 = 5.34 μM), suggesting that it has other anti-cancer mechanisms in addition to CDK4/6." (PMID 34335258, 2021). "CDK4 also presented high selectivity among 15.847 genes, suggesting that this gene is a promising drug target for selective synthetic lethality of cancer cells." (PMID 34771654, 2021). "The largest retrospective cohort of patients treated purely with first-line CDK4/6i + AI was ascertained from the Flatiron Health Database, which at the time of their analysis had collected information from 2 million cancer patients across 275 cancer centres in the US." (PMID 34207443, 2021). "CDK4/6 signaling can become overactive in cancer cells via genetic or epigenetic mechanisms." (PMID 34830174, 2021). "In addition, data from other cancer types suggest several more putative mechanisms of resistance: CDK4/6 overexpression, p16 amplification, upregulation of FGFR pathway, alteration of Hippo pathway, activation of CDK2, autophagy, and epigenetic alterations." (PMID 34071228, 2021). "A number of anti-cancer strategies, which are based on chemotherapy, radiotherapy and immunotherapy or the use of CDK4/6 inhibitors and epigenetic modulators may promote cellular senescence in cancer and normal cells and tissues as an adverse side effect." (PMID 34139673, 2021). "A combination of nobiletin with a CDK4/6 inhibitor may be a new therapeutic strategy to overcome the resistance of a single agent CDK4/6 inhibitor in cancer (especially RCC) treatments." (PMID 33628597, 2021). "Intrinsic resistance to CDK4/6 inhibitors hinders their clinical utility in cancer treatment." (PMID 34459131, 2021).
cancer (continued). "Targeting CDK4/6 activity has long been considered a promising approach for cancer treatment." (PMID 33931578, 2021). "Furthermore, unsubstituted fascaplysin was demonstrated to affect cell cycle machinery in cancer cells via CDK4/6 inhibition." (PMID 34564151, 2021). "Indeed, CDK4/6 inhibition is a hot topic and anticipated to be a therapeutic option for various cancers." (PMID 34075561, 2021). "However, the clear correlation between elevated levels of cyclin D1 protein in cancer cells and CDK4/6 inhibitor sensitivity is yet to be definitely confirmed." (PMID 33805800, 2021). "Therefore, the action of cyclin-dependent kinases 4/6 (CDK4/6) by regulating the transition from G1-to-S cell-cycle phase is crucial for normal and cancer cell proliferation." (PMID 33477469, 2021). "Noteworthy, the efficacy of combinations of ET with mTOR, PI3K, and CDK4/6 inhibitors, the biological interplay between these pathways and the sensitization of cancer mutant cells led to the design of clinical studies investigating triplet combinations [,22,23,]." (PMID 33812267, 2021). "In this context, we therefore focused on whether CDK4 can affect the invasion and metastasis of cancer cells in HCC." (PMID 34784846, 2021). "Given the significance of microRNAs in the regulation of cancer-related pathways, it could be speculated that miRNAs may also play an essential role in response to CDK4/6 inhibitors." (PMID 34439268, 2021). "Targeting this unique PAK combination, could greatly improve the efficacy of CDK4/6i and broaden the spectrum of cancer treatment." (PMID 34138895, 2021). "In addition, it also exhibited significant activity in Hep3B cells which lacks functional Rb gene, suggesting that it has other anti-cancer mechanisms in addition to CDK4/6." (PMID 34335258, 2021). "On the other hand, CDK4 may also be used as an effective therapeutic target key hub gene in the cancer pathway." (PMID 34784846, 2021). "On the other hand, V-ATPase activity is required for necrosis-like death of yeast cells and Caenorhabditis elegans neurons induced by stress and killing human cancer cell lines with CDK4/6 inhibitors, likely by creating an acidic environment that mediates specific cell death pathways." (PMID 34296747, 2021). "We believe selective inhibition of the unique PAK combination responsible for synergy could greatly improve the efficacy of CDK4/6 inhibition and broaden the spectrum of cancer treatment." (PMID 34138895, 2021). "Oncomine, TIMER and GEPIA web-based tools were used to evaluate and validate the mRNA expression of CDK-1 and CDK-4 in different cancer types (solid tumor and hematological malignancies), different CRC sections as well as clinico-pathological parameters of CRC in relation to normal tissues." (PMID 33732631, 2021). "Finally, it is important to note that CDK4 inhibitors have achieved good therapeutic effects in some other cancer studies." (PMID 34784846, 2021). "For example, the proto-oncogenes K-RAS and BRAF, the mitogen-activated protein kinase (MAPK), the extra-cellular signal-regulated kinase (ERK), the phosphoinositide 3-kinase (PI3K)-PTEN-AKT, and CDK4/6-Rb signaling play essential roles in cancer initiation, promotion, and progression." (PMID 33807122, 2021). "EGFR initiates a signaling cascade that leads to DNA synthesis and cell proliferation; and EGFR and PI3K initiate malignant transformation of cancer cells by activating other pathways such as Myc and Rb-E2F, which in turn leads to the formation of cyclinD/Cdk4 and cyclinE/Cdk2 complexes." (PMID 34658851, 2021). "Acquired resistance to SERDs may translate into decreased sensitivity to CDK4/6 inhibitors in a subgroup of ER+ tumors where cancer cells have developed a complete independence from ER for growth and survival." (PMID 33602273, 2021). "Thus, the independent activation of CDK4 serves as a survival mechanism activated in mesenchymal cancer cells allowing escape from MEK inhibitors." (PMID 34309585, 2021).
cancer (continued). "Furthermore, acute CDK4/6 inhibitor treatment reduced the percentage of cells in S/G2 in a variety of normal and cancer cells, suggesting that G1 extension and less efficient cell-cycle entry are general phenomena in CDK4/6-inhibited cells." (PMID 33082317, 2020). "ZEB1 plays pivotal roles in the induction of EMT and cancer metastasis, which led us to examine whether CDK4/6 inhibition could regulate cancer metastasis via ZEB1." (PMID 32296027, 2020). "We found that the protein levels of CDK4 as well as p-RB and Cyclin D1 were down-regulated by wogonin in RCC cells, suggesting that wogonin may exert anti-cancer efficacy by suppressing CDK4 and Cyclin D1 expression." (PMID 32792963, 2020). "CDK4/6 is often dysregulated and overactive in cancer, leading to uncontrolled proliferation." (PMID 32488085, 2020). "Moreover, CDK4 cognate cyclin “cyclin D1” is commonly upregulated in several cancer types such as breast, lung, bladder, and GIT cancers." (PMID 32349307, 2020). "Additionally, EV RNA sequencing revealed an enrichment of miRNAs, targeting different molecules linked to cancer progression (e.g., cyclin-dependent kinase (CDK) family: CDK2, CDK4, and CDK6) and cancer-survival signalling (PIK3R, RAS, MAPK, and STAT)." (PMID 32942702, 2020). "Thus, CDK4/6 represents an oncoprotein that affects cancer cells in both cell cycle-dependent and -independent manners, with the cell cycle-independent property to be exploited for the development of new strategies." (PMID 32249776, 2020). "The principle CDK4/6 inhibitors lost in cancer are CDKN2A and CDKN2B." (PMID 32242058, 2020). "Interestingly, recently deregulated CDK4/CDK6 levels were closely associated with immune suppression and control of cancer immune surveillance." (PMID 32754302, 2020). "PAL/HCQ have been chosen given that CDK4/6i may induce cancer cell autophagy as a stress-tolerance response, evidenced by upregulation of various autophagic markers via a reactive oxygen species (ROS)-mediated mechanism." (PMID 32843618, 2020). "We also discovered a highly active IAP-based degrader that induced the degradation of CDK4/6 as well as the IAPs themselves, which may facilitate killing cancer cells that require IAPs for survival." (PMID 33133483, 2020). "The present study evaluated the synergistic efficacy of using licochalcone B (LCB) and fullerene C60 (FnC60) nanoparticles against diethylnitrosamine (DEN)-induced hepatocarcinoma in rats and relevant signaling pathways, with APE1/Ref-1 and CDK-4, as novel anti-cancer- targeting." (PMID 33841550, 2020). "We next aimed to investigate whether upregulation of SIRT3 by the CDK4/6 inhibitor PD0332991 could enhance the anti-cancer effect of sorafenib on HCC cells." (PMID 32306906, 2020). "However, recently it was reported that fascaplysin can kill cancer cells independently from the presence and activity of CDK4, suggesting other molecular targets to be involved in its mechanism of action." (PMID 33271756, 2020). "Lack of access to innovative cancer therapies, like CDK4/6i, is associated with a significant number of premature deaths of MBC patients." (PMID 32863875, 2020). "And 23 of the 25 functional genes were significantly up-regulated in COAD, such as CDK1, CDK2, CDK4, CDK6, and CDK7, which can cause uncontrolled proliferation and may serve as promising targets in cancer therapy." (PMID 32680494, 2020). "Similarly, agents that selectively block CDK4/6 have been reported to enhance radiosensitivity in cancer cells." (PMID 33042843, 2020). "However, we believe that the combination of CDK4/6i and PARPi is highly likely to show synergy in other cancer types as well." (PMID 32249776, 2020). "Notably, combined inhibition of CDK4/6 and PARP showed synergy in both RB-proficient and RB-deficient cancer cells." (PMID 32249776, 2020). "CDK4/6 inhibitors represent a promising new cancer treatment option." (PMID 31673890, 2020). "CDK4 and p21 are strongly affected mainly in the two cancer cell lines." (PMID 32292575, 2020).
cancer (continued). "Among the various players active in the cell cycle, cyclin D1 and CDK4/6 (cyclin-dependent kinases 4 and 6) are major proteins responsible for progression through G1 to S phases, and regulation of this step is corrupted in many cancers." (PMID 32033319, 2020). "Moreover, increased levels of D-type cyclins and CDK4 are commonly observed, which makes inhibitors targeting the cyclin D-CDK4/6-RB pathway ideal candidates for cancer therapeutics." (PMID 32933570, 2020). "The preclinical data presented here strongly support the clinical testing of PI3K/mTOR pathway inhibitors, in particular p110α-selective PI3K inhibitors such as alpelisib, in patients with ER+/HER2−breast cancer experiencing disease progression on CDK4/6-based therapies." (PMID 32795346, 2020). "Notably, CDK4/6 inhibitors are small selective, orally bioavailable molecules able to restrain proliferation of sensitive cancer cells, preventing cell cycle progression." (PMID 33317149, 2020). "Indeed, CDK4/6 inhibitors have been successfully applied in cancer patients to improve the prognosis of OC patients." (PMID 32595416, 2020). "One of the classic targets of Rsv in cancer cells is the cyclin D1/CDK4 complex." (PMID 33204396, 2020). "The CDK4/6-cyclin D-Rb pathway has been identified as a rational target for cancer therapy." (PMID 32626773, 2020). "Therefore, CDK4 inhibition is featured as a potential strategy for targeted treatment of several cancers through cell cycle arrest within the G1 phase." (PMID 32349307, 2020). "CDK4 could regulate cell cycle from G1 phase to S phase and the overexpression of CDK4 was essential for certain cancer progress." (PMID 33009370, 2020). "Deletion of CDKN2A made cancer cells more sensitive to a selective activity inhibitor of CDK4/CDK6." (PMID 32860670, 2020). "Secondly, would loss of p27 in cancer not universally reduce the activity of CDK4, a formidable oncogene with multiple targets?" (PMID 33166394, 2020). "Alterations in the components of the cell cycle machinery have been frequently reported in cancer; given the success obtained with the CDK4/6 inhibitor palbocicib in ER-positive BC, we explored the potential of combining this drug with chemotherapy in Rb-positive TNBC cell models." (PMID 31506466, 2019). "Importantly, blocking the activity of CDK4/6 synergized with immune checkpoint blockade enhanced the cancer cell immunogenicity and subsequent clearance by cytotoxic T-cells." (PMID 31681564, 2019). "Thus, it is noteworthy that ApoE knockout and knockdown led to decreased expression of cyclin D1 and its associated proteins CDK4 and CDK6, in urethane-induced lung tumors, lung metastases, and cancer cell lines." (PMID 31275318, 2019). "At the present, the cyclin D/Cdk4,6 complexes are considered relevant targets for cancer therapy." (PMID 31426542, 2019). "It inhibits the growth of cancer cells by inhibiting CDK4/6." (PMID 31429774, 2019). "Initially, it was hypothesized that the amplification of CCDN1 could make cancers more dependent on the CDK4/6 pathway and therefore more vulnerable to strategies of CDK4/6 inhibition." (PMID 30959874, 2019). "Consequently, selective and reversible inhibitors of CDK4/6 activity such as palbociclib, ribociblib and abemaciclib block the cell cycle at the G1 phase and thereby prevent cancer progression." (PMID 30959874, 2019). "While the connection between CDK4/6 activity and antitumor T cell function has been established by several seminal reports, it remains unclear whether this role of CDK4/6 exists in non-cancer contexts." (PMID 30863749, 2019). "Until now, there has been no report on CDK4/6 mutations in cancer patients and their effect on efficacy of CDK4/6 inhibitors." (PMID 31058077, 2019). "The inhibition of the PI3K signalling pathway increased sensibility of the cancer cells to CDK4/6 inhibitors palbociclib through a mechanism that could be partially attributable to the suppression of post-mitotic CDK2 activity." (PMID 30959874, 2019).